ENSG00000270149 (novel transcript, TSTD1 - F11R readthrough)
Gene: Protein-coding gene on chromosome 1 (160,997,957 to 161,038,962, reverse strand). Ensembl gene ENSG00000270149.
Genetic constraint (gnomAD): Missense variants: 6 observed, 3.19 expected, observed/expected ratio (o/e) 1.88, 90% interval 0.86 to 1.96. Synonymous variants: 1 observed, 0.48 expected, observed/expected ratio (o/e) 2.08.